PRL (prolactin)
Diseases named in the same sentence as PRL in open-access papers (continued):
Sharing a sentence is not in itself a finding about the gene and the disease.
glioma (11 papers, 2013 to 2025). A benign or malignant brain and spinal cord tumor that arises from glial cells (astrocytes, oligodendrocytes, ependymal cells). "PRL has been known to be associated with the occurrence of neoplasms and central nervous system neoplasms, and so an assessment with PRL expression in primary central nervous system tumors was investigated." (PMID 31865908, 2019). "In the BrM/Glioma group, 8 DEPs (PRL, SNCA, MACF1, ACAT2, VWF, GSN, FCGBP, and F10) were selected for ROC curve analysis based on a logistic regression model." (PMID 39716938, 2025). "Nevertheless, this growing body of evidence suggests that circulating levels of PRL should be closely monitored in glioma patients." (PMID 31862900, 2019). "This upregulation in PRL expression according to glioma grade was also observed when we stratified patient populations by their biological sex." (PMID 31862900, 2019). "The aim of this study was to evaluate prolactin expression in primary central nervous system tumors through quantitative real-time PCR and immunohistochemistry (IH)." (PMID 23317095, 2013). "Moreover, further development of lower grade glioma models is required to clarify why the activation of PRL/PRLR signalling elicit opposite outcomes between GII-III and GBM patients." (PMID 31862900, 2019). "It is therefore tempting to speculate that the combined application of ES and Tum triggers up-regulation of PRLR in glioma, resulting in augmented PRL signalling and ultimately in increased tumor growth and/or stimulation of angiogenesis." (PMID 24257371, 2013). "Moreover, we found a 4fold up-regulation of PRL expression in PRLR-overexpressing cells when compared to mock-transfected cells, suggesting a PRL-autocrine loop that stimulates glioma cell growth." (PMID 24257371, 2013). "However, only little is known about the role of the PRLR/PRL-signaling axis in glioma cells." (PMID 24257371, 2013). "In the Glioma/NC group, 8 proteins (COL1A1, PRL, VWF, HBD, SF3B1, NME3, RRBP1, and CSRP1) were selected, with an AUC of 0.892 in the training set and 0.871 in the validation set (accuracy: 78.5%)." (PMID 39716938, 2025). "Our study proposes PRLR as a therapeutic target for the treatment of GBM and warrants further evaluation of PRL and PRLR as prognostic biomarkers in glioma patients." (PMID 31862900, 2019). "To identify the specific PRL that might play a more important role in GBM development, we examined the expression level of PTP4As in gliomas and their correlation with patient survival using TCGA and GTEx data." (PMID 38904264, 2024). "We next aimed to evaluate the expression of PRL and PRLR in human glioma samples." (PMID 31862900, 2019). "Summarizing, PRL/PRLR signalling may elicit very different outcomes depending on the biological sex of the patient and glioma grade, factors that need to be taken into consideration before translating therapies using PRLR antagonists to the neuro-oncology clinic." (PMID 31862900, 2019). "When we examined the survival of glioma patients according to the local expression of PRL or PRLR we found no significant changes, neither in the overall survival of PRL+ vs. PRL− GII-III or GBM patients, nor in the overall survival of PRLRHIGH vs. PRLRLOW." (PMID 31862900, 2019).
Glucose intolerance (11 papers, 2011 to 2025). Glucose intolerance (GI) can be defined as dysglycemia that comprises both prediabetes and diabetes. "Moreover, prolactin has been found to promote inflammation, which is a risk factor for metabolic alterations, particularly glucose intolerance." (PMID 40896214, 2025). "Serotonin participates in beta cell adaptation, acting downstream of the prolactin pathway; the blocking of serotonin receptor B (HTR2B) signaling in pregnant mice impaired beta cell expansion and caused glucose intolerance." (PMID 37480094, 2023). "Additional progesterone and prolactin from the placenta in a pregnancy state could lead to glucose intolerance by inhibiting insulin action resulting in GDM." (PMID 41013820, 2025).
hyperandrogenism (11 papers, 2008 to 2025). Excessive secretion of androgens from the adrenal glands or gonads. "A revised 2003 consensus on diagnostic criteria of PCOS emphasized that the upper normal limit or slightly above normal PRL levels might be observed in the majority of women with hyperandrogenism." (PMID 36552931, 2022). "Beyond its established role in PRL suppression, CAB demonstrated promising potential in reducing androgen excess, particularly in PCOS with elevated PRL cases, and improving clinical outcomes, without inducing notable changes in FSH or LH levels." (PMID 40399716, 2025). "In addition to hyperandrogenism, hormonal imbalances in PCOS including elevated LH, AMH, prolactin, and inhibin levels." (PMID 40898340, 2025). "The current study is the first to show similar relationships between hyperandrogenism and the absence of prolactin-lowering properties in women." (PMID 37685540, 2023).
male infertility (11 papers, 2012 to 2026). The inability of the male to effect fertilization of an ovum after a specified period of unprotected intercourse. "Although the functional significance of prolactin in male reproduction is unclear, the hormone has been linked mainly with male infertility." (PMID 33663539, 2021). "Data shows the significant association of elevated serum levels of LH, FSH, PRL and low level of Testosterone with male infertility." (PMID 32405170, 2020). "Androgen receptor polymorphisms/mutations and endemic stress generated by fluctuating peripheral prolactin levels, prevalent across the globe are potential causes for the occurrence of chromatin condensation defects associated with male infertility." (PMID 23241214, 2012). "Although prolactin's physiological importance for male reproduction remains uncertain, high levels of this hormone have been associated with male infertility, probably due to a direct deleterious effect on spermatogenesis and the inhibition of pulsatile gonadotropin release." (PMID 36303626, 2022). "Therefore, the present study has been undertaken to comprehensively evaluate the variations in the serumlevels of LH, FSH, testosterone and PRL and also determine their association with different types and subtypes of male infertility in north Indian patients." (PMID 32405170, 2020). "Moreover, data regarding the association ofdifferent serum levels of PRL with male infertility is scanty and controversial." (PMID 32405170, 2020). "Assessment of PRL levels should be remembered during the diagnosis of male infertility." (PMID 38370355, 2024). "Overall, our findings underscore the importance of hormonal balance—particularly concerning LH, PRL, and testosterone—in maintaining optimal sperm quality while also highlighting the need to consider other influences for a comprehensive understanding of male infertility." (PMID 40940756, 2025). "Interestingly, ROC analysis depicted serum PRL as a predictor for male infertility." (PMID 32405170, 2020). "However, there was considerable individual variation in serum levels of inhibin B and PRL, which shows that these hormones are not useful in diagnosis and prediction of live birth in women with unexplained and male infertility." (PMID 23844631, 2013).
meningioma (11 papers, 2013 to 2025). A generally slow growing tumor attached to the dura mater. "In summary, there are currently three underlying prolactin-related theories of drastic meningioma volume changes observed during and after pregnancy: angiogenesis, osmotic regulation and proliferative activity." (PMID 34359779, 2021). "This study sets out to investigate prolactin and prolactin receptor status in 29 patients with pregnancy-related meningiomas in Denmark, from January 1972 to December 2016, as compared to 68 controls aged 20–45 years, also undergoing resection of a meningioma." (PMID 34359779, 2021). "Prolactin was found in elevated levels in the sera of our Grade I meningioma patient group in our study." (PMID 31649887, 2019). "Considering that prolactin stimulates growth of primary meningioma cells in vitro, further studies are necessary to reveal the clinical importance of serum prolactin levels in meningioma patients." (PMID 31649887, 2019). "Regarding meningiomas, Jimenez-Hakim and colleagues demonstrated that PRL concentrations stimulated the growth of meningiomas significantly." (PMID 23317095, 2013). "In this case–control study including the majority of patients with pregnancy-related meningiomas in Denmark 1972–2016, we investigated the presence of prolactin and the prolactin receptor status in the resected meningiomas, compared to meningiomas from female controls within the same age group." (PMID 34359779, 2021). "Estrogen, progesterone, and prolactin levels are elevated during pregnancy, and the expression of the estrogen receptor (ER) and progesterone receptor (PR) has been found in a significant percentage of meningiomas." (PMID 34645501, 2021). "Prolactin has been suggested as a possible key contributor to pregnancy-related meningioma growth." (PMID 34359779, 2021). "The authors speculate that meningiomas supplied by the anterior circulation may be exposed to prolactin." (PMID 34359779, 2021). "Authors of a previous review paper raised the hypothesis that prolactin may be a key contributor to the sudden growth seen in pregnancy-related meningiomas." (PMID 34359779, 2021). "Potential anti-neoplastic effects of phenoxybenzamine may also occur through prolactin or glucocorticoid related pathways in meningiomas." (PMID 29558515, 2018). "Compared to the control group, Grade I meningioma patients showed increased serum levels of amphiregulin (AREG), CCL24, CD69, prolactin, EGF, HB-EGF, caspase-3, and decreased levels of VEGFD, TGF-α, E-Selectin, BAFF, IL-12, CCL9, and GH." (PMID 31649887, 2019). "In conclusion, the results of this study do not support the notion of prolactin being a key contributor to the sudden growth observed in some meningioma patients during pregnancy." (PMID 34359779, 2021). "In conclusion, our results did not support the notion of prolactin as a key contributor to pregnancy-related meningioma growth." (PMID 34359779, 2021). "None of the samples stained positive for prolactin and very few meningioma cells stained positive for prolactin receptors, being equally distributed among pregnancy-related meningiomas and meningiomas from controls." (PMID 34359779, 2021). "Thus, our results did not support the notion of prolactin being a key contributor to pregnancy-related meningioma growth." (PMID 34359779, 2021). "However, no prolactin was discovered in the meningioma cells in this study." (PMID 34359779, 2021). "However, we did not detect an increase in prolactin levels in meningioma tissues." (PMID 31649887, 2019).
anemia (10 papers, 2010 to 2025). A reduction in the number of red blood cells, the amount of hemoglobin, and/or the volume of packed red blood cells. "However, research has reported that high prolactin is one of the principal causes of menstrual disturbances, which can subsequently lead to iron deficiency anemia due to excessive menstrual blood loss." (PMID 40535391, 2025). "Other hormonal factors that were not measured (such as estrogen and progesterone) might mediate or modify this relationship, or the multifactorial nature of anemia in this population could dilute any direct association with prolactin levels." (PMID 40535391, 2025). "Elevated prolactin levels can lead to disturbances in the menstrual cycle and are often linked with heavy or irregular menstrual bleeding, which can be one of the reasons for causing iron deficiency anemia over time." (PMID 40535391, 2025). "The study participants' prolactin levels were measured, and the prevalence of anemia was determined by measuring hemoglobin levels." (PMID 40535391, 2025). "It has been demonstrated that PRL can stimulate human hematopoietic CD34 + progenitor cells and that treatment with drug inducing PRL release (e.g. metoclopramide) improved the hematocrit in subgroups of patients with anemia." (PMID 39900728, 2025). "The severe anemia group also had significantly higher levels of cord blood prolactin, insulin, and placental lactogen compared to the moderate anemia group, but these were not significantly different from the non-anemic group." (PMID 37764824, 2023). "Administration of erythropoietin has been shown to correct anemia, suppress prolactin levels, improve general health status, induce sexual drive, stimulate regular menstruation, and, ultimately, promote fertility." (PMID 24198990, 2013). "Moreover, it is significant to acknowledge that patients with CKD commonly experience lowered erythropoietin levels and exhibit heightened levels of prolactin, which ultimately leads to an increased incidence of anemia and decreased levels of hemoglobin." (PMID 38348104, 2024). "More robust molecular studies are needed to explore the association between prolactin and PPCM in human subjects and to determine the extent to which iron deficiency (with or without anaemia) contributes to the risk of PPCM." (PMID 33060142, 2020). "Considering that anemia might negatively affect the energy of individuals and that both HCT and Hb increased in these patients at follow-up, we would have expected that the increase in HCT and Hb was significantly correlating with the QoL of the patients with normalized PRL." (PMID 39900728, 2025).
cervical cancer (10 papers, 2013 to 2025). A primary or metastatic malignant neoplasm involving the cervix. "In several types of cancer, including breast, ovarian, endometrial, and cervical cancers, PRL can have a causal role due to local production or accumulation." (PMID 33162942, 2020). "A variant of prolactin (PRL) is produced by cervical cancer cells." (PMID 31284453, 2019). "Logistic regression analysis showed that prolactin, red blood cell count, and age were risk factors for cervical cancer, while FSH was a protective factor for cervical cancer." (PMID 39678493, 2024). "Increased serum PRL levels has been reported in approximately one third of patients with cervical carcinoma, PRL being normalized after surgical removal of the tumor." (PMID 33162942, 2020). "Ten years later, the ectopic production of PRL by cervical carcinomas has been demonstrated in cultures of cervical carcinomas." (PMID 33162942, 2020). "qPCR was used to evaluate the effect of E2 and PRL on the expression of E6 and E7 oncoproteins in HeLa and SiHa cervical cancer cells lines." (PMID 31507337, 2019). "Cervical cancer cell lines HeLa, SiHa and C-33 A were stimulated with PRL (200 ng/mL) for 30 and 60 min and non stimulated cells were used to measure basal protein expression." (PMID 26346346, 2015). "A previous study reported that the presence of PRL is increased in cervical cancer tissue from patients compared with controls." (PMID 26346346, 2015). "Our data suggests that STAT3 is an important signaling pathway activated by PRL in cervical cancer cells and it modulates the induction of antiapoptotic genes." (PMID 26346346, 2015). "STAT3 induction in cervical cancer cell lines was the only pathway that showed activation after PRL stimulus compared to HaCaT." (PMID 26346346, 2015). "PRL expression in tissues and serum has been found elevated in patients with cervical cancer suggesting a possible participation in the development or progression of the disease." (PMID 24148306, 2013). "In another work, they reported an increment of serum PRL levels in a considerable number of patients with cervical cancer." (PMID 24148306, 2013). "There are few studies that have focused on the analysis of PRL/PRLR in cervical cancer where the development of neoplastic lesions is influenced by the variation of the hormonal status." (PMID 24148306, 2013). "It has also been reported that PRL may regulate anti-apoptotic gene induction via STAT3 activation in cervical cancer cells." (PMID 38276281, 2024). "Furthermore, it has been observed that treatment with PRL results in a protective effect conferring inhibition of apoptosis in cervical cancer (CC) cell lines." (PMID 34745013, 2021). "Since the beginning of the 1980s, a relatively high incidence of abnormal serum PRL levels has been reported in women with cervical carcinomas, and the use of dopamine agonists as adjunctive treatment for cervical cancer has been hypothesized." (PMID 33162942, 2020). "However, there are no investigations focused on the induction of antiapoptotic genes in cervical cancer in response to PRL/PRLR." (PMID 26346346, 2015). "Additionally, an increase in serum PRL levels was reported in a considerable number of patients with cervical cancer." (PMID 26346346, 2015). "However, few studies have reported the induction of PRL/PRLR in cervical cancer, so their role has been poorly studied." (PMID 26346346, 2015). "Due to activation of STAT3 and the over-induction of antiapoptotic genes found on cervical cancer cell lines after PRL stimulation, we decided to inhibit the STAT3 activation using the inhibitor AG490; which resulted in an impaired induction of Bcl-xl, Bcl-2, survivin and Mcl-1." (PMID 26346346, 2015). "Our data supports the hypothesis that the use of an effective PRL antagonist may provide a better therapeutic intervention in cervical cancer." (PMID 24148306, 2013). "The use of an effective PRL antagonist may provide a better therapeutic intervention in cervical cancer." (PMID 24148306, 2013).